PTPRZ1 (protein tyrosine phosphatase receptor type Z1)
Diseases named in the same sentence as PTPRZ1 in open-access papers (continued):
Sharing a sentence is not in itself a finding about the gene and the disease.
meningioma (4 papers, 2020 to 2023). A generally slow growing tumor attached to the dura mater. "Among these genes, we find that FOXM1, CDH2, and PTPRZ1 are heterogeneously expressed in individual meningiomas." (PMID 32968068, 2020). "High ADC regions in meningiomas correlate with areas overexpressing the CDH2 and PTPRZ1 genes, which drive meningioma tumorigenesis and may represent novel therapeutic targets." (PMID 36497370, 2022). "This CRISPR-induced repression attenuated tumor cell proliferation and was valuable in defining the potential role of chromodomain helicase DNA binding protein 2 (CHD2) and Protein Tyrosine Phosphatase Receptor Type Z1 (PTPRZ1) as novel targets for molecular therapy to treat meningioma patients." (PMID 33800815, 2021). "In contrast, PTN expression in meningioma cells decreased over time in 3D monoculture conditions, perhaps explaining the loss of PTPRZ1 expression from meningioma cells in the absence of a tumor microenvironment." (PMID 32968068, 2020). "To understand the function of these genes in meningioma, we develop a human cerebral organoid model of meningioma and validate the high ADC marker genes CDH2 and PTPRZ1 as potential targets for meningioma therapy using live imaging, single cell RNA sequencing, CRISPR interference, and pharmacology." (PMID 32968068, 2020). "Then, they repressed two key genes involved in meningioma proliferation (CHD2 and PTPRZ1) by transducing cells with lentiviruses harboring the single guide RNA (sgRNA) targeting the genes." (PMID 33800815, 2021). "A minority of meningioma cells in 2D culture expressed genes enriched in regions with elevated ADC, such as CDH2 and PTPRZ1." (PMID 32968068, 2020). "PTPRZ1 has also been included in a group of four genes comprising a gene signature that has been evaluated for the automation of the prediction of 35 brain tumors, distinguishing between GBM and meningioma cases." (PMID 37175798, 2023). "We performed immunofluorescence for Ki-67 and found that repression of CDH2 and PTPRZ1 each attenuated meningioma cell proliferation compared to cells transfected with non-targeting sgRNAs (sgNTC)." (PMID 32968068, 2020). "There was also a meningioma cell cluster enriched for CDH2 and PTPRZ1 that was present after 12 h in 3D monoculture, but not after 14 days, suggesting that neither 2D nor 3D monoculture conditions accurately recapitulate the in vivo molecular heterogeneity of meningioma cells." (PMID 32968068, 2020).
multiple sclerosis (4 papers, 2012 to 2022). A progressive autoimmune disorder affecting the central nervous system resulting in demyelination. "The 2 that were up-regulated, were only altered in the OB: Ptprz1 (protein tyrosine phosphatase, receptor-type, Z polypeptide 1) is expressed in the remyelinating oligodendrocytes of multiple sclerosis lesions; and Pmp22 (peripheral myelin protein 22) is a component of myelin." (PMID 22403656, 2012).
renal cell carcinoma (4 papers, 2010 to 2023). "In contrast, PTPRZ1 is overexpressed in renal cell carcinomas following the loss of VHL activation, activates β-catenin, and enhances cell proliferation." (PMID 37175798, 2023). "The potential role of HIF-2 upregulation of PTPRZ1 in renal cell carcinoma of particularly intriguing, as VHL is associated with renal cell carcinoma and there is evidence that HIF-2 is more important than HIF-1 in the renal cell carcinoma tumorigenesis in this setting." (PMID 20224786, 2010). "In renal cell carcinoma cell lines, downregulation of PTPRZ1 expression by siRNA has been shown to decrease the amounts of nuclear β-catenin, decrease the expression of target genes, and suppress cell proliferation." (PMID 37175798, 2023). "Chronic oxidative stress induces genomic amplification of the Ptprz1 gene in renal cell carcinoma cells, while doxorubicin has been shown to upregulate PTPRZ1 expression in triple-negative breast cancer cells." (PMID 37175798, 2023). "PTPRZ1 can enhance β-catenin protein expression in the nucleus of human renal cell carcinoma and participates in regulating proliferation by activating β-catenin and its downstream genes." (PMID 35251170, 2022). "In the rat renal cell carcinoma model, β-catenin pathway regulated by PTPRZ1 was the mediator of rat renal cell carcinoma carcinogenesis." (PMID 35251170, 2022). "In renal cell carcinoma cell lines, β-catenin has been found to co-immunoprecipitate with PTPRZ1, and downregulation of PTPRZ1 by siRNA led to increased tyrosine phosphorylation of β-catenin and a significant decrease of nuclear β-catenin, leading to decreased cell proliferation." (PMID 37175798, 2023). "However, in another study in human renal cell carcinoma cells, PTPRZ1 was shown to increase nuclear β-catenin protein levels and enhance cell proliferation." (PMID 37175798, 2023). "However, PTPRZ1 mRNA levels are decreased in renal cell carcinomas." (PMID 37175798, 2023).
small cell lung carcinoma (4 papers, 2012 to 2023). Small cell lung cancer (SCLC) is a highly aggressive malignant neoplasm, accounting for 10-15% of lung cancer cases, characterized byrapid growth, and early metastasis. "The oncogenic protein tyrosine phosphatase receptor type Z1 (PTPRZ1), found in highly malignant small-cell lung carcinoma, induced the inactivation of this phosphatase upon binding its ligand pleiotrophin, resulting in increased levels of phospho-Tyr-CaM." (PMID 38136610, 2023). "Activation of the PTN/PTPRZ1 signaling pathway has also been shown to induce calmodulin phosphorylation in small-cell lung cancer cells." (PMID 37175798, 2023). "In contrast, PTPRZ1 is highly expressed in small-cell lung carcinoma cells and human neuroendocrine tumor tissues, having an important oncogenic role in a mouse xenograft model of tumor progression." (PMID 37175798, 2023).
cervical cancer (3 papers, 2023 to 2025). A primary or metastatic malignant neoplasm involving the cervix. "Some recent studies on GSE64217 datasets examined the expression levels of IGF2PB3 and PTPRZ1 genes, suggesting a marker for cervical cancer prognosis in CC samples and normal samples." (PMID 41266827, 2025).
neuroendocrine tumor (3 papers, 2012 to 2024). "Here we show that PTPRZ1, a member of the protein tyrosine- phosphatase receptor (PTPR) family, is highly expressed in SCLC cell lines and specifically exists in human neuroendocrine tumor (NET) tissues." (PMID 23170925, 2012).
prostate carcinoma (3 papers, 2018 to 2025). A carcinoma that arises from epithelial cells of the prostate gland. "In prostate cancer, PTPRZ1 mRNA levels are significantly decreased compared to normal prostate tissue." (PMID 37175798, 2023). "Activation of the cell surface chondroitin sulfate (CS) proteoglycan PTPRZ1 leads to increased tyrosine phosphorylation of several signaling pathways and is upregulated in many human cancers, such as lung cancer, prostate cancer, and glioma, regulating cancer cell migration and metastasis." (PMID 29796177, 2018). "This is in line with data showing that downregulation of PTPRZ1 expression in human prostate DU145 and PC3 cells initiated EMT and enhanced prostate cancer cell migration and invasion in vitro, and metastasis in vivo." (PMID 37175798, 2023). "Through the cell membrane functional complex of ανβ3 and PTPRZ1, PTN also activates xanthine oxidase to produce signaling levels of reactive oxygen species, required for PTN-induced endothelial and prostate cancer cell migration." (PMID 37175798, 2023).
renal carcinoma (3 papers, 2010 to 2023). A carcinoma arising from the epithelium of the renal parenchyma or the renal pelvis. "While PTPRZ1 expression was initially thought to be largely limited to the central nervous system, it has been shown that PTPRZ1 is overexpressed in a variety of tumors, including hepatocarcinoma and renal carcinoma." (PMID 20224786, 2010). "PTPRZ1 knockdown could reduce the number of nuclear β-catenin and inhibit cell proliferation, as well as reduce target genes cyclin D1 and c-myc expressions in renal cancer." (PMID 35251170, 2022).
brain cancer (2 papers, 2022 to 2024). A primary or metastatic malignant neoplasm affecting the brain. "We also found that the less-studied phosphatase PTPRZ1 is a useful target, especially in brain cancer." (PMID 35338126, 2022). "Strikingly, one gene, PTPRZ1 (protein tyrosine phosphatase receptor zeta 1), appears far more frequently than others, especially in three brain cancer data sets (GSE70630, GSE89567, GSE102130)." (PMID 35338126, 2022). "The much lower relative level of PTPRZ1 expression in GSE84465 is likely due to the heterogeneity of brain cancer types in this data set46." (PMID 35338126, 2022). "There have been some attempts to inhibit PTPRZ1 pharmacologically in brain cancer and other brain disorders." (PMID 35338126, 2022).
cardiac hypertrophy (2 papers, 2021 to 2022). "In both mouse and zebrafish animal models, loss of PTPRZ1 results in dilated left ventricle cavity, decreased ejection fraction, and fraction shortening, with no signs of cardiac hypertrophy." (PMID 34767486, 2021). "In mice, PTPRZ1-deficiency resulted in left ventricular dilation, a decrease in ejection fraction and fraction shortening as well as induction of angiogenesis without cardiac hypertrophy." (PMID 36204583, 2022).
colorectal cancer (2 papers, 2022 to 2023). A primary or metastatic malignant neoplasm that affects the colon or rectum. "PTPRZ1 mRNA levels are decreased in colorectal cancers compared to those in adjacent normal mucosae." (PMID 37175798, 2023). "In a following study that involved 102 colorectal cancer tissues, amplification in the region containing the Ptprz1 gene was observed in 20% of cases." (PMID 37175798, 2023). "In a promoter methylation analysis of 131 surgical specimens obtained from patients with sporadic colorectal cancers, the Ptprz1 promoter was found hypermethylated in tumor cells compared to the corresponding adjacent normal tissue, supporting a decreased PTPRZ1 expression in colorectal cancer." (PMID 37175798, 2023).
epilepsy (2 papers, 2015 to 2018). A brain disorder characterized by episodes of abnormally increased neuronal discharge resulting in transient episodes of sensory or motor neurological dysfunction, or psychic dysfunction. "The high-hubs in community C are either involved in mechanisms related to epilepsy pathogenesis (DFF40 and PTPRZ1) or in the control of gene expression and translation initiation (LARP4, EIF1)." (PMID 26011637, 2015).
gastric ulcer (2 papers, 2016 to 2019). An ulcerated lesion in the mucosal surface of the stomach. "Interestingly, Fujikawa and colleagues showed that mice deficient for Ptprz1 were resistant to gastric ulcer induced by Heliobacter pylori." (PMID 27898738, 2016).
inflammatory bowel disease (2 papers, 2018 to 2022). A spectrum of small and large bowel inflammatory diseases of unknown etiology. "PTPRZ1 involvement has been linked to various inflammatory diseases such as inflammatory bowel disease (IBD) and lupus nephritis, where PTPRZ1 expression was found to correlate with IL-34, CSF1, and CSF-1R expression." (PMID 36530919, 2022). "In some other reports, PTN was found not the only activation of PTPRZ1 pathway, inflammation and immune can also activate the PTPRZ1 pathway, such as interleukin (IL)-34, an important receptor of PTPRZ1, promotes the expression of PTPRZ1 in inflammatory bowel disease (IBD)." (PMID 30497491, 2018).
lymphoma (2 papers, 2015 to 2023). A malignant (clonal) proliferation of B- lymphocytes or T- lymphocytes which involves the lymph nodes, bone marrow and/or extranodal sites. "PTPRZ1 expression is also increased in lymphoma tissues from patients with diffuse large B lymphoma, especially of high risk, correlates with the proportion of tumor-associated macrophages that promote lymphoma growth, and coincides with an increased proportion of cancer stem cells." (PMID 37175798, 2023).
melanoma (2 papers, 2019 to 2022). A malignant, usually aggressive tumor composed of atypical, neoplastic melanocytes. "Similarly, genes related to melanoma invasion were downregulated in SIRT2-deficient melanoma cell lines (e.g., HLA-DRA, IL-6, CD74, and HLA-DRB1 in the SSW30 clone, Dataset S1; PTPRZ1, FST, and NRCAM in the SSM15 clone, Dataset S2)." (PMID 31091806, 2019).
neuroblastoma (2 papers, 2021 to 2023). Neuroblastoma (NB) is the most common solid, extracranial childhood tumor. "PTPRZ1 substrates with potential relevance in neuroblastoma include ALK, TrkA, p190 RhoGAP, β-catenin, and SFK, among others." (PMID 34957126, 2021). "Modulation of PTPRZ1 activity using specific ligands or pharmacological inhibitors could be an alternative treatment for neuroblastoma that needs to be explored." (PMID 34957126, 2021). "In addition, regulated glycosylation of PTPRZ1 in neuroblastoma cells also induces its dimerization and catalytic inactivation, suggesting a tight physiologic control of constitutive PTPRZ1 catalytic activity." (PMID 34957126, 2021). "In neuroblastoma cells, this leads to increased tyrosine phosphorylation of p190 RhoGAP, GIT1, and DNER, and it has been proposed that the PTN inhibitory effect on PTPRZ1 acts as a major ALK indirect activating mechanism." (PMID 34957126, 2021).
oral submucous fibrosis (2 papers, 2022 to 2023). "On the other hand, PTPRZ1 overexpression promotes oral submucous fibrosis, a potentially malignant disease of the oral cavity, through the nuclear translocation of β-catenin." (PMID 37175798, 2023). "Overexpression of PTPRZ1 promotes the malignant transformation of oral submucous fibrosis, at least partly, through its effect on β-catenin phosphorylation." (PMID 37175798, 2023).
pancreatic cancer (2 papers, 2023). "The PPARα agonist clofibrate downregulates the expression of PTPRZ1 in pancreatic cancer cells, by abrogating the binding of nuclear factor-κB (NFκΒ) to the Ptprz1 promoter." (PMID 37175798, 2023).
triple-negative breast carcinoma (2 papers, 2023 to 2024). An invasive breast carcinoma which is negative for expression of estrogen receptor (ER), progesterone receptor (PR), and human epidermal growth factor receptor 2 (HER2). "In triple-negative breast cancer (TNBC) tissues that had relapsed after chemotherapy, the expression of PTN and its receptor PTPRZ1 was found to be elevated, which was closely linked to a poor prognosis." (PMID 39759507, 2024). "In triple-negative breast cancer cells, NFκΒ is activated downstream of PTPRZ1 following PTN binding, although the signaling that leads to NFκΒ activation is not clarified." (PMID 37175798, 2023). "Doxorubicin enhanced both PTPRZ1 and PTN expression in the triple-negative breast cancer MDA-MB-231 and MDA-MB-453 cells, promoting cell proliferation and inhibiting apoptosis through PTPRZ1-dependent activation of NFκΒ." (PMID 37175798, 2023).
uveal melanoma (2 papers, 2022 to 2023). A melanoma derived from melanocytes of the uveal tract. "In uveal melanoma cells, PTPRZ1 is overexpressed and positively affects proliferation and invasion in vitro." (PMID 37175798, 2023). "A more recent approach developed for the treatment of highly aggressive uveal melanoma was the construction of indocyanine green-labeled manganese metal-organic framework nanoparticles that carry siRNA for the lncRNA OUM1 and PTPRZ1, together with cisplatin." (PMID 37175798, 2023).
autism (1 paper, 2011). Persistent deficits in social interaction and communication and interaction as well as a markedly restricted repertoire of activity and interest as well as repetitive patterns of behavior. "By examining our expanded list of genes, we found several more of our connectivity linked genes are in AUTS1 and have been studied in the context of autism: Reln, Mest, Ptprz1, Dpp6 and En2." (PMID 21253556, 2011).
experimental autoimmune encephalomyelitis (1 paper, 2023). An autoimmune demyelinating disease of the central nervous system that is produced experimentally in animals by the injection of homogenized brain or spinal cord in Freund's adjuvant. "In the spinal cord of Ptprz1-deficient C57BL/6 mice with experimental autoimmune encephalomyelitis, Tyr1105 phosphorylation in p190 Rho GAP was independent of Fyn, supporting the notion that p190 Rho GAP is a PTPRZ1 substrate." (PMID 37175798, 2023).
gastric adenocarcinoma (1 paper, 2023). "In stomach adenocarcinoma, positive PTPRZ1 immunohistochemical reactivity has been observed and has been associated with gastric cancer progression." (PMID 37175798, 2023). "However, PTPRZ1 mRNA levels are significantly lower in gastric adenocarcinoma compared to the corresponding normal tissue." (PMID 37175798, 2023).
head and neck cancer (1 paper, 2022). A primary or metastatic malignant neoplasm affecting the head and neck. "PTPRZ1 was the fifth most frequently occurring gene in optimal solutions for the head and neck cancer data set (GSE103322)." (PMID 35338126, 2022). "Emerging individual targets include PTPRZ1 for brain and head and neck cancers and EGFR in multiple tumor types." (PMID 35338126, 2022). "PTPRZ1 also occurs commonly in optimal solutions for the head and neck cancer data set." (PMID 35338126, 2022).
hepatoma (1 paper, 2010). "In each of two cell lines studied, Hep3B (derived from human hepatoma cells) and HEK293T (derived from human embryonic kidney cells), substantially more PTPRZ1 promoter activity, as assessed using a luciferase reporter assay, was observed in response to HIF-2α as compared to HIF-1α." (PMID 20224786, 2010).
hyperlysinemia (1 paper, 2013). Hyperlysinaemia is a lysine metabolism disorder characterized by elevated levels of lysine in the cerebrospinal fluid and blood. "In two patients originating from one family, the hyperlysinemia was caused by a contiguous gene deletion syndrome affecting AASS and PTPRZ1." (PMID 23570448, 2013).
neurotoxicity (1 paper, 2022). Toxicity that causes injury to the central or peripheral nervous system or damages its function. "Ptprz1 was differentially expressed in 6 postoperative periods of Neurotoxicity, Blood–brain barrier and Cognitive function, and it could negatively regulate oligodendrocyte precursor proliferation." (PMID 35899365, 2022).
Osteopenia (1 paper, 2015). Osteopenia is a term to define bone density that is not normal but also not as low as osteoporosis. "Of note, although Ptprz1-deficient mice only displayed a moderate osteopenia at 1 year of age, primary osteoblasts derived from newborn Ptprz1-deficient mice had an increased proliferation rate compared to wildtype cultures." (PMID 26360410, 2015).
osteosarcoma (1 paper, 2023). A usually aggressive malignant bone-forming mesenchymal neoplasm, predominantly affecting adolescents and young adults. "In a sample of 30 osteosarcoma patients, the Ptprz1 gene was overexpressed in 73% and under-expressed in 27% of cases." (PMID 37175798, 2023).